HGF (hepatocyte growth factor)
Diseases named in the same sentence as HGF in open-access papers (continued):
Sharing a sentence is not in itself a finding about the gene and the disease.
ovarian carcinoma (continued). "HGF, through activation of the MAPK and phosphatidylinositide-4,5-bisphosphate 3-kinase (PI3K)/AKT pathways, promotes phosphorylation of p70S6K, which induces EMT in ovarian cancer cells by increasing expression of Snail and MMP9." (PMID 26356073, 2015). "We have addressed the effect of HGF, and subsequent inhibition of c-MET, on migration of ovarian cancer cells in both directional (chemotactic) and random migration assays, to more accurately recapitulate the environment and proteins encountered in an in vivo setting." (PMID 26138303, 2015). "For example, heparin-binding EGF-like growth factor (HB-EGF), neuregulin-1 beta (NRG1β), insulin-like growth factor 1 (IGF1), and hepatocyte growth factor (HGF) are all expressed in tumors and found at higher levels in ascites fluid of ovarian cancer patients compared to healthy controls." (PMID 26648788, 2015). "In addition, it seemed that EGF and HGF cooperate to promote invasiveness in ovarian cancer cell lines through increase secretion of MMP9 and the inhibition of MMP9 abolished EGF and HGF induced cellular invasion." (PMID 23320251, 2012). "Studies showed that NK4 could inhibit ovarian cancer cell migration, tumor growth, and peritoneal dissemination in vivo, indicating that NK4 could be an attractive target for therapy in inhibiting HGF/MET pathway." (PMID 23320251, 2012). "RNA interference (RNAi) against MACC1 could serve as a promising intervention strategy for gene therapy of ovarian carcinoma, and the antitumor effects of MACC1 knockdown might involve in the inhibition of HGF/Met and MEK/ERK pathways." (PMID 21923915, 2011). "As a key regulator of HGF/Met signaling, RNA interference against MACC1 could serve as a promising intervention strategy for gene therapy of ovarian carcinoma." (PMID 21923915, 2011). "In ovarian carcinoma cells, the antitumor effects of MACC1 RNAi might involve in the inhibition of HGF/Met and MEK/ERK pathways." (PMID 21923915, 2011). "Interestingly, the production of colony‐stimulating factor‐1 (CSF‐1), hepatocyte growth factor (HGF), and epidermal growth factor (EGF) by ovarian cancer cells, endothelial cells, and TAMs, respectively, and the formation of a paracrine loop was shown to be crucial for metastatic progression." (PMID 38411356, 2024). "HGF and GRO-1 promote the cellular senescence of mesothelial cells and increase the production of hyaluronic acid, u-PA (urokinase plasminogen activator), IL-8 (interleukin-8), and MCP-1 (monocyte chemotactic protein-1), which stimulate cell adhesion, proliferation, and migration in ovarian cancer." (PMID 38791014, 2024). "However, determining the precise origin of sHGF in ovarian cancer patients is complex because elevated HGF levels are not unequivocally specific for cancer, as they were also reported in infections or graft‐versus‐host disease." (PMID 33738970, 2021). "However, increased sMET levels in ovarian cancer patients with an unfavourable prognosis do not necessarily allow the conclusion that these tumours have increased HGF/cMET signalling." (PMID 33690968, 2021). "Western blotting analysis also showed that CAF-derived HGF or recombinant HGF activated c-Met/phosphoinositide 3-kinase (PI3K)/Akt and glucose-regulated protein 78 (GRP78) signalling pathways in ovarian cancer cells, and these effects could be abrogated by anti-HGF and c-Met inhibitor INCB28060." (PMID 28258248, 2017). "Indeed, we found contact-dependent secretion by hMSCs of CCL10 (IP-10), CCL5 (RANTES), HGF, and GM-CSF in third party co-cultures with ovarian cancer cell lines and hMSCs (data not shown)." (PMID 20436665, 2010). "Furthermore, some studies showed that HGF does not increase the viability of ovarian cancer cells." (PMID 31355133, 2019). "However, in ovarian cancer, it seemed that HGF/MET did not regulate angiogenesis." (PMID 23320251, 2012).
ovarian carcinoma (continued). "To determine if HGF/c-MET signaling mediated cell migration in endometriosis and non-HGSC ovarian cancer, we first assessed c-MET expression level using qRT-PCR." (PMID 40076450, 2025). "Several therapeutics, including small molecules and antibodies, such as foretinib, cabozantinib and YYB-101, have been developed that target the HGF/c-MET pathway and have been tested in clinical trials in ovarian cancer patients, yet none has shown significant efficacy." (PMID 40076450, 2025).
myeloma (86 papers, 2005 to 2025). "In bone disease associated to multiple myeloma, the production of IL-11 is stimulated by hepatocyte growth factor (HGF)." (PMID 34201209, 2021). "Hepatocyte growth factor (HGF)/c‐met pathway activation has been implicated in the pathogenesis of multiple myeloma (MM), and blocking this pathway has been considered a rational therapeutic strategy for treating MM." (PMID 30353654, 2018). "We and others have previously shown that serum HGF levels are elevated in myeloma patients compared with normal controls, and associated with poor prognosis." (PMID 18691255, 2008). "Furthermore, the multi-specific DARPin® molecule, MP0250, was shown to strongly neutralize VEGF and HGF causing a significant reduction in the number of vessels and was defined as a novel combination drug for treatment of multiple myeloma patients." (PMID 31575023, 2019). "The HGF/c-Met pathway has been associated with the development of numerous solid tumours and has been implicated in the pathogenesis of MM with the discovery of an autocrine loop and the pathogenesis of myeloma bone disease." (PMID 29924867, 2018). "The hepatocyte growth factor/c-MET pathway has been implicated in the pathobiology of multiple myeloma, and c-MET inhibitors induce myeloma cell apoptosis, suggesting that they could be useful clinically." (PMID 28337527, 2017). "Similarly, high HGF levels in serum were also associated with poor prognosis in myeloma: serum HGF levels decreased when the treatment proved effective, and increased again towards relapse." (PMID 25119536, 2014). "This could be of value in clinical applications, and in particular in relation to the bone disease of multiple myeloma, where elevated HGF levels associate with severity of disease." (PMID 24716444, 2014). "However, its ligand HGF is increased in plasma or serum obtained from myeloma patients and higher HGF level has been associated with poor prognosis." (PMID 24326130, 2013). "Interestingly, single nucleotide polymorphisms of the HGF gene have been associated with myeloma risk." (PMID 22567028, 2012). "In this context, 2 key myeloma markers, MYC and DKK1, as well as many other cancer-associated genes, including ADM, HDGF, IL15, HGF, STMN1, CDKN1B and CD82, were potentially regulated by the predicted ligands." (PMID 41056512, 2025). "Shed SDC-1 retaining intact HS chains has been shown to complex with HGF and translocate to the nuclei of myeloma cells." (PMID 41301515, 2025). "Investigations of multiple myeloma have shown that (i) both HGF and c‐Met signaling are involved in the growth of MM cells, and (ii) the plasma concentration of HGF is related to disease progression and/or prognosis." (PMID 36825580, 2023). "The upregulation of heparinase in myeloma and BC cells is associated with increased release of sEVs containing syndcan-1, VEGF and HGF, and with enhanced tumor cell proliferation and massive invasion of endothelial cells through TME." (PMID 36499561, 2022). "Elevated heparinase levels in myeloma and BC cells have also been linked to increased release of syndecan-1, VEGF and hepatocyte growth factor (HGF) in sEVs, resulting in increased endothelial invasion via TME." (PMID 36499561, 2022). "Recent phase II clinical trials have, however, reported safe systemic application, e.g. the drug candidate MP0250, an anti-VEGF/HGF DARPin for the treatment of multiple myeloma." (PMID 33721106, 2021). "HGF is produced by myeloma cells and an elevated level of HGF has been demonstrated in the serum of MM patients compared to healthy individuals." (PMID 34201396, 2021). "As TGF-β1 and IL-1 overload the impact of HGF on IL-11 production, it was postulated that HGF from myeloma cells induces MMBD via IL-11." (PMID 34163520, 2021). "When the cytokine production of MM-MSCs in response to the RPMI8226 myeloma cell line was examined in a 3D culture of gelatine sponge scaffolds, higher secretion of IL-11 and HGF and less IL-10 was observed as compared to 2D cultures." (PMID 34067236, 2021).
myeloma (continued). "In the presence of hypoxic conditions, myeloma cells upregulate hypoxia induced factor 1α (HIF1α), which regulates transcription of pro-angiogenic cytokines including HGF, bFGF, VEGF, and Angiopoietin-2 (Ang-2)." (PMID 33634031, 2020). "HMCL and primary myeloma express the tyrosine kinase HGF receptor, c-Met, and produce HGF at variable levels." (PMID 33634031, 2020). "Tivantinib, a Met inhibitor, reduced tumor burden and inhibited myeloma-induced bone disease in vivo; a Met antagonist inhibited HGF-induced MM cell proliferation, survival, migration, and adhesion, and reversed HGF-induced inhibition of osteoblastogenesis." (PMID 33114380, 2020). "Numerous studies have instead clearly established a key role for the HGF/c-MET axis in promoting myeloma cells aggressiveness." (PMID 30642077, 2019). "Immunohistochemical staining of bone samples from myeloma patients showed concomitant expression of HGF and c-Met in MPCs." (PMID 29924867, 2018). "To find a suitable human myeloma cell line for in vitro assays and an in vivo study, we quantified the gene expression of HGF in 5 human myeloma cell lines and healthy plasma cells by real-time PCR, relative to the housekeeping gene GAPDH." (PMID 29924867, 2018). "Cell surface proteoglycan syndecan-1 (CD138) is highly expressed in multiple myeloma cells and function as a coreceptor for HGF that promotes HGF/Met signaling in MM cells." (PMID 30237983, 2018). "Subsequently, a number of studies noted expression of HGF by myeloma cell lines and purified primary myeloma cells." (PMID 29924867, 2018). "HGF levels have been found to be elevated in the serum of myeloma patients compared to healthy matched controls, and this has correlated with a poor prognosis." (PMID 29924867, 2018). "Syndecan 1 (CD138) on myeloma cells binds HGF and promotes c-MET signaling, while both potentiate interleukin-6-induced growth and migration, correlating with shorter survival." (PMID 28337527, 2017). "The median plasma HGF level in myeloma patients was 450 pg/mL (range 150–5991) at baseline and was <600 pg/mL in the majority (10/16), while the HGF levels in the two healthy donors were 60 and 1400 pg/mL." (PMID 28337527, 2017). "Conversely, declining HGF levels are seen in patients responding to anti-myeloma therapies, and patients with low HGF levels were more likely to achieve high-quality responses." (PMID 28337527, 2017). "The c-MET receptor tyrosine kinase proto-oncogene regulates cell growth, survival, and migration, and c-MET signaling after engagement of its ligand, HGF, is a contributor to the pathogenesis of myeloma." (PMID 28337527, 2017). "This is supported by the data showing that HGF increases adhesion of multiple myeloma cells on FN by activating the MAPK/ERK pathway, also dependent on VLA-4 expression." (PMID 29017538, 2017). "The orally bioavailable ATP-competitive MET inhibitor amuvatinib, currently in trials for the treatment of solid tumors, has been shown to result in cell death in myeloma cells known to be dependent on HGF/MET signaling." (PMID 27655636, 2016). "We previously demonstrated that MM cell-derived HPSE not only induced an aggressive phenotype in myeloma cells, but also promoted angiogenesis via the secretion of soluble factors, such as HGF, VEGF and soluble syndecan-1, from myeloma cells." (PMID 26849235, 2016). "HGF bound to GAGs on the surface of myeloma cells was able to be displaced by sulfated alginates indicating that the HGF had a higher affinity for the sulfated alginates than natural HS on the cell surface." (PMID 25751786, 2015). "Bone marrow levels of soluble SDC1 and HGF were elevated in multiple myeloma patients compared to control subjects." (PMID 26293675, 2015). "It is the major proteoglycan secreted by multiple myeloma cells affecting bone mineralization growth of myeloma cell in vivo and secretion of hepatocyte growth factor (HGF)." (PMID 26581653, 2015).
myeloma (continued). "For example, the binding of HGF with SDC1 enhances downstream signaling in myeloma cells, osteoblasts, and stromal cells." (PMID 26293675, 2015). "By performing co-cultivation experiments of BMSC with various myeloma cell lines we found that co-cultures of stromal cells with ANBL-6 cells or JJN3 cells led to a marked increase in HGF production." (PMID 24716444, 2014). "Cultivation of myeloma cell lines separated from BMSC by a permeable membrane in transwell experiments showed that soluble factors alone are sufficient for increased HGF production." (PMID 24716444, 2014). "This indicates that stromal cells are only able to induce elevated HGF production in myeloma cells which already are capable of making HGF." (PMID 24716444, 2014). "To address this we co-cultivated bone marrow stromal cells (BMSC) with various myeloma cell lines for 48 hours, before measuring the produced HGF present in the co-culture supernatant by ELISA." (PMID 24716444, 2014). "The data showing that BMSCs increase HGF production in myeloma cells is consistent with the view that myeloma cells largely rely on and respond to the bone marrow niche." (PMID 24716444, 2014). "In summary these data indicate that the myeloma cells are the primary source of HGF in the bone marrow of myeloma patients with elevated levels of HGF." (PMID 24716444, 2014). "The main result presented here is that in multiple myeloma malignant plasma cells are the prime source for the high HGF levels in the bone marrow and peripheral blood serum." (PMID 24716444, 2014). "We have earlier shown that myeloma cell lines as well as primary myeloma cells often significantly overexpress HGF." (PMID 24716444, 2014). "HGF mRNA levels in bone marrow core biopsies from healthy individuals and myeloma patients were quantified by real-time PCR." (PMID 24716444, 2014). "We have earlier shown that about 50% of myeloma patients have elevated HGF protein levels in the blood serum and in the bone marrow as compared to healthy individuals." (PMID 24716444, 2014). "HGF serum values are frequently (approx. 50%) elevated in myeloma patients and a subgroup of myeloma patients, i.e. approximately 30%, shows highly elevated HGF serum concentrations." (PMID 24716444, 2014). "HGF gene expression profiling in both bone marrow core biopsies and CD138+ cells showed elevated HGF mRNA levels in myeloma patients." (PMID 24716444, 2014). "This is quite surprising because the blood serum levels of HGF have been reported to be abnormal in myeloma, acute myeloid leukaemia (AML), chronic myelogenous leukaemia (CML) andmyeloproliferative neoplasms (MPNs)." (PMID 25119536, 2014). "Collectively, these findings strongly suggest CD138+ cells as the main source of excess HGF in myeloma patients." (PMID 24716444, 2014). "We therefore investigated its origin and found that HGF mRNA levels were significantly elevated in bone marrow core biopsies of myeloma patients if compared to mRNA values in biopsies of healthy individuals." (PMID 24716444, 2014). "Investigating the molecular mechanisms behind the HGF production in myeloma cells, we looked for genetic aberrations possibly responsible for the excess HGF production." (PMID 24716444, 2014). "Considering the fact that elevated HGF serum and plasma levels predict poor prognosis, these findings are of particular importance for patients harbouring a myeloma clone which produces large amounts of HGF." (PMID 24716444, 2014). "We and others have earlier reported that about 50% of myeloma patients have elevated serum levels of HGF." (PMID 24716444, 2014). "As shown in previous studies, HGF protein levels in plasma and serum from myeloma patients show large variations and we here confirm this on the mRNA level measured in CD138+ cells." (PMID 24716444, 2014).